INS (insulin)
Diseases named in the same sentence as INS in open-access papers (continued):
Sharing a sentence is not in itself a finding about the gene and the disease.
Insulin resistance (continued). "This is a cross-sectional study among 335 adolescents who provided both dietary information assessed using a validated food frequency questionnaire (FFQ) and biochemical parameters including lipid profile, blood glucose, serum insulin and homeostatic model assessment-insulin resistance (HOMA-IR)." (PMID 32280358, 2020). "However, during the development of T2DM disease, with the occurrence of insulin resistance, the decrease of insulin levels, the development of fatty liver, the liver 18F-FDG gradually decreased." (PMID 32647998, 2020). "Furthermore, adiponectin is an important insulin-sensitizing adipocytokine that is downregulated in insulin resistance and obesity, and replenishment of this protein in adiponectin-deficient state improves insulin sensitivity." (PMID 32463311, 2020). "One point of view posits that the increased demand for insulin secretion in the setting of insulin resistance overwhelms the capacity of β cells to produce insulin, largely as a result of the incapacity of the endoplasmic reticulum to accommodate protein throughput." (PMID 33353164, 2020). "To elucidate the molecular mechanism underlying RFRP-3-mediated insulin resistance, we assessed whether RFRP-3 regulates the insulin-associated AKT-GSK3-β signaling cascade." (PMID 32328034, 2020). "An in vivo animal study using SHBG transgenic mice compared with wild type mice found that overexpression of SHBG protects against high fat diet (HFD) induced obesity and insulin resistance, as evidenced by lower glucose profiles during glucose tolerance tests and insulin tolerance tests." (PMID 33139661, 2020). "Alcohol overconsumption may promote the pathogenesis of hepatic insulin resistance by inhibiting insulin signaling." (PMID 32508647, 2020). "Possibly, lipid-induced insulin resistance may also have affected carnitine uptake and may have blunted the insulin-induced carnitine storage in muscle." (PMID 32976523, 2020). "Moreover, compared with men, women have a more distinct association between abdominal visceral adipose tissue and insulin resistance measured by HOMA IR and insulin secretion." (PMID 33033953, 2020). "Additionally, p70 S6K, the downstream effector of mTOR, has been shown to cause serine phosphorylation of IRS-1, resulting in impaired insulin signaling and insulin resistance." (PMID 32230718, 2020). "However, Sphk2-LKO mice exhibited significantly elevated plasma insulin levels and enhanced homeostasis assessment of insulin resistance (HOMA-IR) values under the HFD condition." (PMID 32917816, 2020). "Insulin resistance and T2D represent perturbed metabolic states in which intestinal sensitivity to key regulatory hormones such as insulin, leptin and glucagon-like peptide-1 (GLP-1) may be altered, contributing to increased CM secretion." (PMID 32231641, 2020). "TNF signaling pathway: tumor necrosis factor-alpha (TNF-α), one of the most crucial pro-inflammatory mediator, induced insulin resistance in adipocytes by impairing the insulin signaling through serine phosphorylation so that leading to the development of T2DM." (PMID 33292335, 2020). "On one hand, the low levels of chromium might result in the diminution of insulin signal transduction, and further aggravate the development of insulin resistance." (PMID 32967680, 2020). "Thus, considerable evidence now indicates that the net effect of RANKL signaling is to impair insulin secretion, induce insulin resistance, and increase circulating glucose levels." (PMID 31911667, 2020). "Furthermore, PPARγ3RA/+ mice showed impaired glucose tolerance and insulin tolerance compared to their WT counterparts, suggesting that PPARγ 3RA mutations in mice exacerbate HFD-induced insulin resistance." (PMID 32973516, 2020). "Animal studies confirm that A2BR activation increases serum IL-6 levels, which may be involved in the development of insulin resistance and improve insulin sensitivity." (PMID 32984382, 2020).
Insulin resistance (continued). "In contrast, insulin was shown to stimulate brain glucose metabolism in subjects with impaired glucose tolerance and there have been reports of inverse relations between insulin resistance and CMRglc." (PMID 32265637, 2020). "In mice, early muscle-specific deletion of Growth Hormone Receptor (GHR) causes several symptoms including insulin resistance, while adult muscle-specific GHR deletion causes entirely different effects, including increased metabolic rate and insulin sensitivity on a high-fat diet." (PMID 31944178, 2020). "At the same time, insulin resistance index (HOMA-IR) were calculated by the formula INS*GLU/22.5." (PMID 33362535, 2020). "Systolic and diastolic blood pressure were higher in the UK cohort (p < 0.001), whilst testosterone (p < 0.02), glucose (p < 0.001), WCC (p < 0.001), HDL (P < 0.001), CRP (p < 0.001), insulin and insulin resistance (p < 0.001) were higher in the Middle Eastern cohort without PCOS." (PMID 33144665, 2020). "Supplementation with whey proteins during 12 weeks in overweight and obese subjects was associated with a significant decrease in total cholesterol and LDL- cholesterol and an improvement in fasting insulin concentrations and homeostasis model assessment of insulin resistance (HOMA-IR) scores." (PMID 32958070, 2020). "Thus, insulin resistance impaired insulin action in fibroblasts, resulting in an attenuated inhibitory effect of insulin on 11β-HSD1 expression." (PMID 33260645, 2020). "This protein superfamily could improve insulin sensitivity, decrease insulin resistance, increase glucose tolerance, enhance glucose uptake, and reduce gluconeogenesis." (PMID 32468164, 2020). "Interestingly, FGFR3 expression in scWAT was also negatively correlated with HOMA-IR (homeostasis model assessment of insulin resistance) and fasting plasma insulin concentrations." (PMID 32184391, 2020). "It is well established that there is an inverse relationship between insulin resistance and plasma adiponectin levels, suggesting that adiponectin is an important regulator of insulin sensitivity and glucose homeostasis, possibly through stimulation of AMP-activated protein kinase (AMPK)." (PMID 32047529, 2020). "Further research is warranted to identify dosing and schedule of insulin treatment to improve outcomes for patients suffering from neurological disease and trauma, and to understand the role insulin resistance plays in the development and progression of brain disorders." (PMID 33100956, 2020). "Among computed values derived from glucose and insulin measurements, the homeostatic model assessment of insulin resistance (HOMA-IR score) was most frequently reported with 41 studies, of which 26 (63.4%) demonstrated significant improvement with intervention." (PMID 33003593, 2020). "It is commonly caused by impaired insulin secretion, with or without insulin resistance, and is characterized by hyperglycemia." (PMID 33182561, 2020). "An oral glucose tolerance test was performed at baseline and follow-up to define type 2 diabetes, prediabetes, fasting glucose, fasting insulin, 2-hour glucose, homeostasis model assessment of insulin resistance (HOMA-IR), homeostasis model assessment of beta-cell function and hemoglobin A1c." (PMID 32690629, 2020). "Furthermore, dysregulation of the HPA-axis results in diminished secretion of insulin, and insulin resistance, resulting in a shift from glucose metabolism to lipid metabolism." (PMID 32973137, 2020). "Thereafter, by using the conventional MR method, the inverse-variance weighted method was applied to assess the causal effect of BMI, WHR, and WHRadjBMI on T2DM risk, Homeostatic model assessment of insulin resistance (HOMA-IR), fasting insulin, fasting glucose, and Hemoglobin A1c (HbA1c)." (PMID 32714368, 2020).
Insulin resistance (continued). "In this review, we first describe the insulin signaling pathway in the heart (Section 2.1) and evaluate both current knowledge and discrepancies concerning the molecular mechanisms leading to lipid-induced insulin resistance (Section 2.2)." (PMID 33322406, 2020). "Moreover, oral glucose tolerance test and subcutaneous insulin tolerance test demonstrated that HFD-induced insulin resistance was obviously ameliorated by administration of JT003." (PMID 33199780, 2020). "Numerous studies indicate that visceral obesity is the main cause of insulin resistance and MS; nevertheless, the causes of reduced insulin sensitivity in the target organs are not exactly known." (PMID 32244612, 2020). "Relative to uninterrupted sitting, this strategy may reduce postprandial insulin more in those with high basal insulin resistance, but those with high fasting triglycerides may be resistant to such intervention-induced reductions in triglycerides." (PMID 33308235, 2020). "Along with glucose uptake, we also determined whether our protocol of insulin-induced insulin resistance could affect this cellular function." (PMID 32718202, 2020). "Previous studies suggested that caffeine could improve insulin resistance by stimulating insulin secretion from pancreatic β cells." (PMID 32722627, 2020). "We used a two-sample Mendelian randomization approach to evaluate the causal effect of six glycemic traits (type 2 diabetes, fasting glucose, fasting insulin, hemoglobin A1c, homeostasis model assessment- insulin resistance and HOMA-β-cell function) on Alzheimer’s disease." (PMID 33202379, 2020). "This may indicate that different brain regions respond differently to insulin or insulin resistance." (PMID 32281722, 2020). "A few years ago, we have shown increased PHLPP1 expression in adipose tissue and skeletal muscle biopsies from obese, insulin-resistant subjects and hypothesized that PHLPPs may represent an additional player in insulin resistance." (PMID 32411219, 2020). "Hyperglycemia in patients with type 2 DM may be attributed to reduced insulin secretion from the pancreas and/or to peripheral insulin resistance." (PMID 32706828, 2020). "Moderate estrogens are known to increase insulin sensitivity, but estrogens at supraphysiological levels may induce insulin resistance." (PMID 32345324, 2020). "It is noteworthy that although insulin is known to be a survival hormone, the presence of insulin resistance in diabetes may compromise the protective effect of this hormone." (PMID 32326182, 2020). "The relationship between dietary fructose and insulin resistance in humans is uncertain as excess dietary fructose does not invariably cause elevated insulin concentrations." (PMID 32849314, 2020). "The elevated insulin in the HFD-HFD group was suggestive of insulin resistance." (PMID 32407841, 2020). "Insulin resistance is characterized by a diminished response to insulin stimulation, resulting in the failure of target tissues to adequately dispose of blood glucose, inhibit lipolysis, stimulate glycogen synthesis, and inhibit hepatic glucose output and is a precursor event to type 2 diabetes." (PMID 33167521, 2020). "Indeed, induction of insulin resistance by genetic disruption of insulin signaling, as well as by increased growth hormone levels or an inflammatory milieu, causes hyperinsulinemia." (PMID 32819363, 2020). "We conclude that microbes from obese mice are contributors to impaired insulin clearance during diet-induced obesity, which may contribute to hyperinsulinemia, insulin resistance, and obesity." (PMID 32860984, 2020). "Moreover, the necessity to distinguish between reduced insulin secretion and insulin resistance has been emphasized." (PMID 32992875, 2020). "Hence, a sustained release of high levels of GH significantly contributes to the development of insulin resistance by antagonizing the antilipolytic action of insulin." (PMID 33060792, 2020).
Insulin resistance (continued). "Although the mechanisms are not precise, the detrimental impact of obesity on cognitive function may be, at least in part, due to vascular defects like IR and chronic low-grade inflammation, impaired insulin metabolism or insulin resistance." (PMID 32486256, 2020). "In addition, rutin, another PA constituent, which significantly enhances the insulin release, decreases intestinal glucose absorption, decreases hepatic glucose output, induces the peripheral insulin action and affects mediators of insulin resistance." (PMID 32967670, 2020). "The study revealed that phaeochromocytoma could lead to glucose intolerance by both impaired insulin secretion and increased insulin resistance." (PMID 33324347, 2020). "Indeed, although muscle and liver are insulin resistant in women with PCOS, the ovaries retain normal insulin sensitivity, highlighting the tissue-specificity of insulin resistance in PCOS." (PMID 32308679, 2020). "The mechanisms underlying glucose intolerance have been widely studied, and two factors have been highlighted as crucial: insulin resistance, described previously, and β-cell dysfunction, i.e., the inability of the β cells to secrete appropriate amounts of insulin." (PMID 33324238, 2020). "Therefore, it is suggested that circulating vaspin is increased as a compensatory response to elevated concentration of insulin and enhancing insulin resistance." (PMID 33198735, 2020). "However, insulin has different functions depending on the cell types; therefore, the functional consequences of insulin resistance differ between the target tissues." (PMID 32796572, 2020). "Our results, however, demonstrated that hepatic Sdf2l1 expression was increased in insulin-resistant mice fed a high-fat diet, and that the suppression of increased hepatic Sdf2l1 expression induced by whey protein isolate improved insulin resistance in mice fed a high-fat diet." (PMID 32978487, 2020). "In the present study, higher expression of TLR2 and TLR4 in diabetic patients with kidney failure than in diabetic patients without kidney failure was associated with higher values of HOMA-IR (as indicator of insulin resistance) and lower values of HOMA-IS (as indicator of insulin sensitivity)." (PMID 33442388, 2020). "As reported, OL and HT reduce hyperglycemia, hyperlipidemia, and insulin resistance (IR) in rats with metabolic syndrome and have been proposed as protective against the development of obesity, with the improvement of insulin sensitivity in type 2 diabetes (T2D)." (PMID 33256066, 2020). "In mice exposed to high-fat milk, CA elevated insulin sensitivity and reduced insulin resistance." (PMID 32566690, 2020). "Reduced insulin sensitivity can lead to insulin resistance and compensatory hyperinsulinemia." (PMID 32973686, 2020). "Type I diabetes is caused by a lack of insulin as a result of destroyed β-cells, while type 2 diabetes is the result of insulin resistance." (PMID 33182561, 2020). "Additionally, it outlines important differences in insulin signaling and the development of insulin resistance in these tissues." (PMID 33038072, 2020). "Central insulin effects are mediated via the vagal nerve ACh acting on to the α7nAChR of Kupffer cells and hepatic macrophages, which are dysregulated in high fat diet and insulin resistance and drive many hepatic pathophysiological changes in obesity." (PMID 32260529, 2020). "T1D is characterized by little or no production of insulin by the pancreatic beta‐cells, whereas T2D is characterized by both impaired insulin secretion and insulin resistance, leading to the inability of insulin‐sensitive muscle and adipose tissues to take up glucose." (PMID 31342643, 2020). "Based on several studies conducted on type 1 and type 2 DM animal models, orally or parenterally administrated ASX improves insulin resistance and insulin secretion; reduces hyperglycemia; and exerts protective effects against retinopathy, nephropathy, and neuropathy." (PMID 32660119, 2020).
Insulin resistance (continued). "However, with increasing insulin resistance and decreasing β-cell function, there is decreased insulin-dependent glucose uptake by the skeletal muscles and the liver, as well as ineffective suppression of hepatic glucose production." (PMID 33261162, 2020). "Indeed, insulin resistance and impaired insulin signaling in the central nervous system (CNS) have been linked to the pathogenesis of AD, observations that resulted in terming AD “type 3 diabetes”." (PMID 32075060, 2020). "Anthocyanin might also ameliorate insulin resistance via the activation of insulin signaling and enhanced glucose transporter 4 (GLUT4) translocation, which increases glucose uptake and reduces the hyperglycemia associated with metabolic disorders." (PMID 32973912, 2020). "Blood glucose and insulin are markers of sugar metabolism and insulin resistance." (PMID 33177581, 2020). "Present studies have indicated that EA may improve insulin resistance by enhancing insulin sensitivity in rats." (PMID 33011961, 2020). "Regarding blood tests, the fact that IL-6 and insulin were significantly higher in the high-salt group may suggest insulin resistance." (PMID 33198295, 2020). "Moreover, glucose and insulin are trophic factors that induces islet compensatory growth response to insulin resistance." (PMID 32752280, 2020). "Insulin sensitivity is not only critical for glucose metabolism, but insulin resistance can increase various lipids and alter amino acid metabolism that may also impact HMO composition." (PMID 32722157, 2020). "Patients underwent blood tests for determination of follicle-stimulating hormone (FSH), luteinizing hormone (LH), total testosterone, DHEA-S, estradiol, of sex hormone-binding globulin (SHBG), fasting glucose, insulin, Homeostatic Model Assessment of Insulin Resistance (HOMA-IR), and lipid profile." (PMID 32967289, 2020). "The reason for this result may be because the PCOS patients we selected had lower insulin levels (or insulin resistance), or the enzyme levels of our LOCAH patients were slightly better." (PMID 32892549, 2020). "Since the PI3K-Akt pathway contributes to both insulin resistance and neutrophil phagocytosis, our diabetic model may require long-term insulin therapy for a significant improvement of neutrophil phagocytosis activity." (PMID 32993618, 2020). "A ratio of cerebrospinal fluid to serum insulin levels can help indicate CNS insulin resistance." (PMID 32704569, 2020). "The conflicting pieces of evidence concerning DAG and CER as the sole factors driving the onset of lipid-induced insulin resistance (discussed in Section 2.2) leave room to investigate other maladaptive mechanisms involved in the inhibition of the insulin cascade." (PMID 33322406, 2020). "Insulin resistance is defined as an inefficient response of tissue to normal plasma insulin levels." (PMID 32138327, 2020). "Since adipocyte overgrowth in vivo may be accompanied by the development of insulin resistance, we checked the insulin sensitivity of our cells by determining the phospho‐AKT/AKT ratio at T14, T18 and T22." (PMID 32618419, 2020). "One aspect of T2D is insulin resistance, but the other lies in defective insulin secretion." (PMID 32183037, 2020). "Along with increased insulin resistance, insulin secretion showed a compensatory increase." (PMID 32184821, 2020). "As adiponectin is considered by previous publications as an insulin sensitizer, it may importantly contribute to reduce insulin resistance and promote insulin-sensitizing activity due to the treatment of diabetic rats with quercetin." (PMID 32655759, 2020). "Furthermore, in a group of seventeen HIV-infected subjects, which developed increased insulin-resistance, high doses of Spirulina (19 g daily for two months) significantly increased insulin sensitivity by 224.7%, in comparison with soybean supplementation." (PMID 33348926, 2020).